SERPING1 (serpin family G member 1)
Diseases named in the same sentence as SERPING1 in open-access papers (continued):
Sharing a sentence is not in itself a finding about the gene and the disease.
hereditary angioedema (continued). "Hereditary angioedema (HAE) is a life-threatening autosomal dominant inherited disease, caused by mutations in the SERPING1 gene encoding the serine protease inhibitor (serpin) C1-inhibitor (C1-inh)." (PMID 25369003, 2014). "The diagnosis of hereditary angioedema (HAE) is based on clinical suspicion and the existence of a family history, and requires confirmation through the complement study (C4, C1q, C1 inhibitor, and functional C1 inhibitor) and the SERPING1 gene study." (PMID 38773490, 2024). "We report a heterozygous, 2,009 base pairs (bps) genomic DNA deletion within the SERPING1 gene that has not previously been reported in a case of type I hereditary angioedema (HAE)." (PMID 30923640, 2019). "The absence of sufficient levels of functional SERPING1 leads to hereditary angioedema (HAE), which is mediated by sustained activation of kallikrein leading to cleavage of high molecular weight kininogen (HMWK), producing bradykinin." (PMID 33730015, 2021).
angioedema (221 papers, 2008 to 2026). Swelling involving the deep dermis, subcutaneous, or submucosal tissues, representing localized edema. "Type 1 and type 2 HAE-C1INH share the same pathogenesis of angioedema, mutations in SERPING1, and dysfunctional C1INH, resulting in bradykinin overproduction." (PMID 39596962, 2024). "The same mutation of the SERPING1 gene was detected in his son at the age of 9-months prior to the occurrence of angioedema symptoms, during genetic family counseling." (PMID 38978843, 2024). "Angioedema with C1-inhibitor (C1-INH) deficiency can be hereditary (C1-INH-HAE)—an autosomal dominant disorder caused by mutations in the SERPING1 gene—or acquired (C1-INH-AAE)." (PMID 36726161, 2023). "Twelve other variants located in intron 4 of the SERPING1 gene were described in patients with hereditary angioedema in scientific publications and the HGMD database." (PMID 38255179, 2023). "We aimed to detect mutations in the SERPING1 gene and evaluate its expression in nine probands with hereditary angioedema from nine different families." (PMID 33292549, 2020). "SERPING1 is involved in the regulation of the complement cascade, and its sequence variation mainly causes hereditary angioedema." (PMID 31387199, 2019). "Homozygous carriers have been recognized as symptomatic for angioedema or these variants may have a disease-modifying effect (Section Homozygous and Compound Heterozygous Probands Carrying SERPING1 Variants)." (PMID 35958943, 2022). "These questions may indicate that BK-mediated angioedema comprises a heterogeneous group of multifactorial diseases, even if their pathomechanism can be linked to mutations of a single gene (SERPING1, FXII, ANGPT1, etc." (PMID 33725263, 2021). "Genetic testing of angioedema is primarily focused on detecting alterations in the DNA of genes encoding proteins that are part of the complement, fibrinolysis, coagulation, kinin, and vasculature systems, including C1-INH (SERPING1), FXII (F12), plasminogen (PLG), or angiopoietin-1 (ANGPT1)." (PMID 33560480, 2021). "Targeted re-sequencing of five HAE-associated genes (SERPING1, F12, PLG, ANGPT1, and KNG1) was performed in 212 ACEi/ARB-induced angioedema patients recruited in Germany/Austria, Sweden, and Denmark, and in 352 controls from a German cohort." (PMID 35923707, 2022). "Mutations in SERPING1, the gene that encodes C1-INH (C1 esterase inhibitor), are responsible for the majority of cases of hereditary angioedema." (PMID 34065094, 2021). "The clinical phenotype manifests with disabling and potentially lethal angioedema, i.e. episodic local edema of the subcutaneous and submucosal tissues, when one of the two alleles of C1-INH gene (SERPING1) is mutated." (PMID 29343682, 2018). "Specific mutations in C1-INH (SERPING1) and Factor12 genes alter the contact system and lower the angioedema threshold to clearly pathological levels." (PMID 29107952, 2017). "Viral interactions with SERPING1 may therefore result in excessive levels of complement activation, bradykinin production and angioedema." (PMID 33730015, 2021). "This rare disease is due to a mutation in one of the alleles of the C1-INH gene, SERPING1, which results in reduced plasma levels of C1-INH and dysregulation of the contact system, facilitating an increased release of bradykinin, the key mediator of angioedema." (PMID 25520740, 2014). "HAE with C1–INH deficiency, the first described and most studied, is caused by a mutation in the SERPING1 gene, which encodes the C1 inhibitor protein, causing increased production of bradykinin, a mediator that promotes vasodilation and increased vascular permeability, leading to angioedema." (PMID 39582512, 2024). "Mutations in the SERPING1 gene could not be identified and there was no family history of angioedema." (PMID 30866985, 2019).
angioedema (continued). "In conclusion, the present analyses identified no known disease-causing HAE variant in SERPING1, F12, PLG, ANGPT1, or KNG1 in a cohort of around 200 patients with ACEi/ARB-induced angioedema." (PMID 35923707, 2022). "Deleterious variations in genes responsible for the control of BK release, as SERPING1, or its metabolization, as CPN, CPM, angiotensin-converting enzyme (ACE), and neprilysin (MME), are able to increase the amount of BK released or its half-life, leading to or intensifying angioedema episodes." (PMID 30847342, 2019).
C1 inhibitor deficiency (37 papers, 2011 to 2026). "Knowledge of the SERPING1 mutation allowed the verification of C1-inhibitor deficiency in 24, at the time of the analysis yet symptom-free individuals." (PMID 35386643, 2022).
COVID-19 (37 papers, 2020 to 2025). A disease caused by infection with severe acute respiratory syndrome coronavirus 2. "The severe COVID-19 risk allele for signal-B at TYK2 is associated with reduced SERPING1 and CXCL10 protein expression, implying that the minor allele at signal-B in the TYK2 locus reduces some aspect of TYK2 function." (PMID 36327221, 2022). "Indeed, the SERPING1 transcript, encoding for C1-INH, was found to be increased in the whole blood RNA of COVID-19 patients compared to healthy controls." (PMID 39768234, 2024). "Therefore genetic predisposition to low SERPING1 expression may increase risk for COVID-19 through the same dynamics as reduced levels due to infection." (PMID 36327221, 2022). "Regardless of the tissue type, we saw consistent increases in genes such as B2M, CD81, GNAS, HLA.B, HSPA1A, HSPB1, and SERPING1 in COVID-19 lungs." (PMID 35233546, 2022). "The COVID-19 risk allele (T), that correlates with increased TYK2 transcript expression, correlated with reduced amounts of SERPING1 and CXCL10 proteins in plasma (p = 0.0003)." (PMID 36327221, 2022). "SERPING1, an inhibitor of complement 1 (C1-inh), is known to be reduced by infection and this reduction correlates with more severe COVID-19." (PMID 36327221, 2022). "We focused on the impact of VKORC1, SERPING1, and PABPC4 gene variants on COVID-19 severity." (PMID 33730015, 2021). "On the other hand, the Humoral response GO term, reflecting both complement (SERPING1, C1QB) and B cell activation (JCHAIN, POU2AF1), was progressively more enriched in COVID-19 patients from T1 through T3." (PMID 37365222, 2023). "The gene expression and functional analysis of the early vs. late COVID-19 cases revealed significant differences with increased levels of ADAM17, C1S, SERPING1, and DDIT3 in the early group." (PMID 35163504, 2022). "Network pharmacology analyses identified 6 potential targets (IL6, DPP4, MIF, PRF1, SERPING1, and SLC6A4) for emetine in anti-LUAD/COVID-19." (PMID 35733175, 2022). "To study the role of coagulation in COVID-19 pathogenesis, we explored the interactions of VKORC1, SERPING1 and PABPC4 with viral proteins through computational docking." (PMID 33730015, 2021). "The identification of key immune-modulating genes like ISG15, SERPING1, C1QA, C1QB, and VSIG4 opens avenues for therapeutic approaches that aim to modulate the immune response and improve outcomes in severe COVID-19 cases via upregulation of expression of these genes." (PMID 40374692, 2025). "In addition, we evaluated the potential bindings of emetine with the LUAD/COVID-19 targets (SLC6A4, MIF, DPP4, PRF1, SERPING1, and IL6)." (PMID 35733175, 2022). "In terms of host factors responsible for SARS-CoV-2 entry, the COVID-19 knowledge model highlights the importance of ACE2, TMPRSS2, and components of the ISG response that are specifically dysregulated by SARS-CoV host interaction (ACE2, SERPING1)." (PMID 39086962, 2022). "The concurrent downregulation of ACE2 and SERPING1 may reciprocally amplify the deregulation of KKS, which may in turn lead to a cascading over-activation of downstream signaling, especially in acute COVID-19." (PMID 39086962, 2022). "The validation study using MRM could specifically detect AGT, FGG, APOB, SERPING1, and SERPINA3 host peptides in COVID-19 severe patients." (PMID 33995121, 2021). "Consistently, proteomic and metabolomics data from CMs revealed several genes (KNG1, TXNIP, ITIH4, TIMP1, SERPING1/2/3, ITGA1, ADAR, and CLIC5 etc.)and molecules (adenosine and inosine) were related with platelet activation, thus, adding antiplatelet might be a possible therapeutic for COVID-19." (PMID 35903092, 2022). "Currently, to our knowledge, no therapies for COVID-19 or other infectious diseases have been developed that specifically target ISG15, SERPING1, or VSIG4 genes." (PMID 40374692, 2025).
autoimmune disease (25 papers, 2011 to 2025). A disorder resulting from loss of function or tissue destruction of an organ or multiple organs, arising from humoral or cellular immune responses of the individual to their own tissue constituents. "A systematic review in the literature showed that a deficiency of C1-inhibitor (encoded by SERPING1) was present in autoimmune diseases." (PMID 34349764, 2021). "Moreover, as described in the literature for PRKDC and ORAI1, mutations within SERPING1 can also cause severe forms of inflammatory and autoimmune disorders." (PMID 36294757, 2022). "SERPING1, C3, FGA, FGG, and CFH were significantly related to autoimmune diseases, and C3 in particular is associated with systemic lupus erythematosus (SLE) that shows a similar immunopathogenic basis to pSS." (PMID 34516718, 2021).
Sepsis (21 papers, 2011 to 2025). Sepsis is defined as life-threatening organ dysfunction caused by a dysregulated host response to infection. "Dot plot visualization further confirmed these trends at the gene level, with C3, SERPING1, and HLA-A/B/C being notably upregulated in Astrocyte 2 under sepsis conditions, while EMP1, CLCF1, and PTGS2—representing A2 features—were similarly elevated." (PMID 41030458, 2025). "Notably, these DEPs including Fads2, Fgb, Cypla2, Cyp2e1, Cfb, Serping1, Fgg, Etnppl, Agt, Hsd3b5, Gnmt, A2m, Pck1, Stat3, Ptpn1, Scd1, Slc2a1, and Uox were key genes in liver sepsis, which maybe associated with inflammation in sepsis." (PMID 37255592, 2023).
systemic lupus erythematosus (14 papers, 2012 to 2026). An autoimmune multi-organ disease typically associated with vasculopathy and autoantibody production. "Among them, we identified pathogenic or likely pathogenic variants in genes previously associated with monogenic lupus, including a novel C1QA variant as well as other lupus-associated genes (COPA, ADAR, TLR7, IKZF3, RELA, PTPN11, SERPING1)." (PMID 41930824, 2026). "C3, CFH, SERPING1, FGA, and FGG were significantly enriched in the “complex and coagulation cascades pathway,” C3 was also enriched in the “systemic lupus erythematosus” pathway, and PRB1 in the “salivary secretion” pathway." (PMID 34516718, 2021).
Autoimmunity (13 papers, 2016 to 2025). The occurrence of an immune reaction against the organism's own cells or tissues. "In spite of mutations of the SERPING1 gene, autoimmunity and infections are not prominent features of the condition." (PMID 27965672, 2016).
Stroke (13 papers, 2009 to 2024). Sudden impairment of blood flow to a part of the brain due to occlusion or rupture of an artery to the brain. "Stroke increased gene expression of the proinflammatory A1 astrocyte markers Serping1, Psmb8, Srgn, and Gbp2 in both normotensive and hypertensive mice (P < 0.05)." (PMID 38886874, 2024). "Furthermore, the incidence rates of post-stroke immunological trajectory of post-stroke recovery may also be explained by the immune inhibitory effects of SERPING1, following the initial phase of post-stroke immune flux and subsequent immunosuppression." (PMID 32849183, 2020).
age-related macular degeneration (10 papers, 2009 to 2025). Age-related loss of vision in the central portion of the retina (macula), secondary to retinal degeneration. "SERPING1 has been shown to be associated with age-related macular degeneration and multiple immune-mediated diseases; SERPING1 mRNA is also expressed in both the retina and the retinal pigment epithelium-choroid layers of human donor eyes." (PMID 33643312, 2021). "Deficiencies in SERPING1 have also previously been shown to occur in age-related macular degeneration." (PMID 29967729, 2018). "Single nucleotide polymorphisms (SNPs) in the complement component 1 inhibitor (SERPING1) gene have been shown to be significantly associated with age-related macular degeneration (AMD) in Caucasian populations." (PMID 20062564, 2010). "Recently, SNPs in the serpin peptidase inhibitor, clade G (C1 inhibitor) member 1 (SERPING1) gene showed highly significant genotypic association with age-related macular degeneration in two Caucasian populations." (PMID 20062564, 2010). "Moreover, our results are consistent with previous evidence that genetic variation in SERPING1 significantly alters susceptibility to age-related macular degeneration." (PMID 40770768, 2025). "Recently, a complement component 1 inhibitor (SERPING1) gene polymorphism was identified as a novel risk factor for age-related macular degeneration (AMD) in Caucasians." (PMID 21526158, 2011). "Common genetic variation in the complement component 1 inhibitor gene (SERPING1) was recently reported to increase the risk of developing age-related macular degeneration (AMD)." (PMID 19169411, 2009).
depression (9 papers, 2012 to 2025). "SERPINE1 and SERPING1 were suggested crucial in the promotion of depression in patients with ovarian cancer." (PMID 36699448, 2022).
ischemia (9 papers, 2013 to 2023). A hypoperfusion of the BLOOD through an organ or tissue caused by a PATHOLOGIC CONSTRICTION or obstruction of its BLOOD VESSELS, or an absence of BLOOD CIRCULATION. "The main finding is that 10 genes (Clec5a, CD14, Fgr, Hck, Anxa1, Lgals3, Irf1, Lbp, Ptx3, Serping1) may represent key molecular links underlying acute activation of immune cells in the hippocampus in response to experimental ischemia." (PMID 34944656, 2021). "We found that endothelial markers (Angptl4), and pericyte marker (Cyp1b1, Emp1, S1pr3, Serping1, and Cxcl1) were upregulated in prolonged ischemia." (PMID 35154109, 2022). "Serpin G1 TEX levels in the HF patient group differ between HF patients with and without MI which is in accordance with the association of SerpinG1 with ischemia." (PMID 26820481, 2016). "CD14 and CystatinC protein levels were independent significant predictors of stress-induced ischemia in the LDL and the HDL subfraction and SerpinC1 and SerpinG1 protein levels in the HDL fraction." (PMID 32704130, 2020).
asthma (7 papers, 2017 to 2026). "Phenotype scanning identified associations between rs204993 (AGER, ID = oid20756) and asthma, as well as rs117960683 (SERPING1, ID = 4479_14_SERPING1_C1_Esterase_Inhibitor) and daily smoking." (PMID 40853920, 2025). "Indirectly perturbed genes near ATF3 and EGR2 in the network include C2, SERPING1, ZG16B, and CEACAM3, all of which have been linked to immune response, asthma, or auto-immune diseases." (PMID 33095769, 2020). "TSMR and SMR analyses revealed no causal links between SERPING1 and IPF or asthma, implying that SERPING1 may be a COPD-specific biomarker." (PMID 41559025, 2026).
endothelial dysfunction (7 papers, 2018 to 2025). In vascular diseases, endothelial dysfunction is a systemic pathological state of the endothelium (the inner lining of blood vessels) and can be broadly defined as an imbalance between vasodilating and vasoconstricting substances produced by (or acting on) the endothelium. "In our study, among differentially expressed proteins were PLG, SERPING1, SERPINC1, APOA2, FGB, A2M, which are related to endothelial dysfunction, coagulation processes and pro-atherogenic alteration mechanisms." (PMID 29755368, 2018).
hereditary angioedema type I (7 papers, 2014 to 2025). Hereditary angioedema type 1 (HAE 1) is a form of hereditary angioedema characterized by acute edema in subcutaneous tissues, viscera and/or the upper airway. "Mutations in SERPING1 are responsible for the majority of cases of hereditary angioedema type I and II." (PMID 38978843, 2024). "Hereditary angioedema Types I and II are caused by a mutation in the C1 esterase inhibitor gene (SERPING1)." (PMID 34445711, 2021). "SERPING1 mutations causing Hereditary Angioedema type I (HAE-I) due to C1-Inhibitor (C1-INH) deficiency display a dominant-negative effect usually resulting in protein levels far below the expected 50%." (PMID 25053016, 2014).
breast carcinoma (6 papers, 2021 to 2025). "Noteworthy is our discovery of SERPING1’s potential in early bone metastasis detection in breast cancer, aligning with its diagnostic significance in LUAD." (PMID 39962118, 2025). "It has previously been associated with prevalent breast cancer, incident COPD, an age-by-sex interaction and the levels of 17 proteins including CRP, SERPING1, CHAD and CGA." (PMID 41361833, 2025). "This trend mirrored findings in prostate cancer and breast cancer, where reduced SERPING1 expression corresponded to higher pathological grades, advanced tumor stages, and unfavorable prognoses." (PMID 39962118, 2025). "Studies indicate that SERPING1 can serve as a novel marker for prostate cancer diagnosis and prognosis and is relevant for early detection of bone metastases in breast cancer." (PMID 39445005, 2024). "The outcomes revealed that two hub genes (SERPING1 and GIMAP4) were negatively correlated with breast cancer bone metastasis." (PMID 36246872, 2022).
glioma (6 papers, 2018 to 2025). A benign or malignant brain and spinal cord tumor that arises from glial cells (astrocytes, oligodendrocytes, ependymal cells). "Previously, Fornvik and colleagues demonstrated that the survival rate is increased in rats inoculated intracerebrally with glioma cells precoated with anti‐SERPING1 antibody." (PMID 39474998, 2025). "Additionally, this model and four of its genes (CLECL5A, SERPING1, CHI3L1 and C1R) were found to be associated with immune cell infiltration, and further study demonstrated that these four genes might drive the hypoxic phenotype of perinecrotic GBM, which affects hypoxia‐induced glioma stemness." (PMID 33009892, 2020). "To test the effect of KD on the pro-inflammatory transcriptional profile of glioma cells, we sorted Luc+-GL261 cells from mouse brains and found that none of the tested genes were modulated, while others, such as Serping1, H2-T23, and CD44 were under the limit of detection." (PMID 39921723, 2025).